KIF17 (kinesin family member 17)
Description:
Together with RAB23 and IFT57, it is required for the localization of specific G protein-coupled receptors, such as dopamime receptor DRD1, to primary cilia. In association with the Apba1-containing complex (LIN-10-LIN-2-LIN-7 complex), transports vesicles containing N-methyl-D-aspartate (NMDA) receptor subunit NR2B along microtubules.
Synonyms: KIAA1405; KIF3X; KIF17B; OSM-3; KLP-2
Tractability: Antibody: the Human Protein Atlas places it where antibodies can reach. PROTAC: ubiquitination databases record sites on it.
Gene: Protein-coding gene on chromosome 1 (20,664,011 to 20,718,017, reverse strand). Ensembl gene ENSG00000117245.
Subcellular location: Cytoplasm, cytoskeleton; Cell projection, cilium; Cell projection, dendrite
Subcellular location (Human Protein Atlas): Nucleoplasm; Acrosome; Basal body; Cytosol; Plasma membrane; Primary cilium tip; Principal piece
Pathways (Reactome):
Neuronal System: Assembly and cell surface presentation of NMDA receptors
Organelle biogenesis and maintenance: Intraflagellar transport
Gene Ontology:
Molecular function: protein binding; plus-end-directed microtubule motor activity; ATP binding; microtubule binding; microtubule motor activity
Biological process: anterograde dendritic transport of neurotransmitter receptor complex; microtubule-based movement
Cellular component: cilium; cytosol; kinesin complex; microtubule organizing center; neuron projection; cytoskeleton; dendrite; dendrite cytoplasm
Genetic constraint (gnomAD): Loss-of-function variants: 74 observed, 89.11 expected, observed/expected ratio (o/e) 0.83, 90% interval 0.69 to 1.01. The upper end of that interval is the gene's LOEUF score, 1.01, which puts it in group 4 of 6, group 1 being the genes least tolerant of losing a copy. Missense variants: 1,266 observed, 1,350.2 expected, observed/expected ratio (o/e) 0.94, 90% interval 0.89 to 0.98. Synonymous variants: 561 observed, 581.74 expected, observed/expected ratio (o/e) 0.96, 90% interval 0.9 to 1.03.
Homologues: Orthologues: macaque DDOST (96% identical), chimpanzee KIF17 (89% identical), pig KIF17 (81% identical), dog KIF17 (81% identical), rat Kif17 (81% identical), mouse Kif17 (80% identical), guinea pig KIF17 (80% identical), rabbit KIF17 (76% identical), tropical clawed frog kif17 (51% identical), zebrafish kif17 (47% identical), Caenorhabditis elegans osm-3 (36% identical), Drosophila melanogaster Kif3C (29% identical). Paralogues in human: KIF3B (31% identical), KIF3C (30% identical), KIF3A (29% identical), KIF13A (24% identical), KIF13B (24% identical), KIF1A (23% identical), KIF1B (23% identical), KIF16B (23% identical), KIF11 (21% identical), KIF21A (21% identical), KIF1C (21% identical), KIF21B (20% identical), and 29 more.
Diseases named in the same sentence as KIF17 in open-access papers:
KIF17 is named in the same sentence as 13 diseases in open-access papers, as found by Europe PMC text mining. Sharing a sentence is not in itself a finding about the gene and the disease. The quoted sentences say what the papers report.
breast carcinoma (3 papers, 2017 to 2023). "Consistent with this idea, expression of the KIF17 NR box in breast cancer cells inhibited the expression of a subset of ERR1 gene targets, suggesting that KIF17 is a selective, competitive inhibitor of ERR1 cofactor binding in the nuclear compartment." (PMID 36835206, 2023). "We showed previously that the LxxLL motif contained within the tail domain of KIF17 is both necessary and sufficient to modify expression of ERR1-dependent genes in breast cancer cells." (PMID 36835206, 2023). "Notably, the ability the LXXLL-containing KIF17 NR box peptide to inhibit ERR1 transcriptional activity suggests it could be used, with or without additional modification, as a tool to attenuate ERR1 function in breast cancer." (PMID 28881568, 2017).
schizophrenia (2 papers, 2014 to 2026). A major psychotic disorder characterized by abnormalities in the perception or expression of reality. "Additionally, abnormalities in molecular motors such as KIF17 and KIF1A have been implicated in schizophrenia pathophysiology." (PMID 41972553, 2026).
Anosmia (1 paper, 2016). An inability to perceive odors. "Based on our data, we suggest that KIF17 should be considered as a strong candidate for a modifier in NPHP patient that present with extra-renal manifestations such as blindness and anosmia." (PMID 26863025, 2016).
ciliopathies (1 paper, 2020). "While anosmia was originally associated with Bardet-Biedl Syndrome and Leber congenital amaurosis, two known ciliopathies, it is now known to be associated with a subset of ciliopathies that have mutations in Cep290 or KIF17." (PMID 32993148, 2020).
coloboma (1 paper, 2021). An abnormality in which a part of a structure in one or both eyes is missing. "Our report indicates the potential co-segregation of these biallelic KIF17 variants with microphthalmia and coloboma, highlighting a potential conserved role of this gene in eye development across different species." (PMID 33922911, 2021). "We report a Sicilian family with two siblings affected with an array of congenital eye anomalies consistent with the MAC spectrum in which clinical exome sequencing revealed biallelic segregating compound heterozygous variants in the KIF17 gene associated with coloboma and microphthalmia." (PMID 33922911, 2021).
tumor (6 papers, 2011 to 2023). "In our current study, we performed expression analysis of kinesin family in LUAD which revealed overexpression of KIF11/12/15/23/18B/20A/2C/4A/C1 in tumor samples whereas KIF17/26A/1C were underexpressed in LUAD." (PMID 37330525, 2023).
cancer (2 papers, 2011 to 2023). A tumor composed of atypical neoplastic, often pleomorphic cells that invade other tissues. "Two of the genes (KIF17 and ATP8A2) showed no methylation in either cancer or matched tissues, and eight genes (EPHA4, OVOL1, UTF1, ADAM8, BOLL, FOXE3, GUCY1A2, and ADCY5) were equally methylated in the two groups." (PMID 21625442, 2011).
psychiatric disorder (1 paper, 2025). A disorder characterized by behavioral and/or psychological abnormalities, often accompanied by physical symptoms. "Therefore, we examined the messenger RNA (mRNA) expression levels of psychiatric disorder-related Kifs in each microglial substate and the morphology of microglia stimulated by interleukin (IL)-4 which possess a mutation inducing truncated KIF17." (PMID 39885501, 2025). "As a candidate for a crucial Kifs gene that is likely related to microglia polarization, we selected psychiatric disorder-related KIFs (KIF3A, KIF17, KIF1A, KIF1B, and KIF13A)." (PMID 39885501, 2025). "KIF3A and KIF17 that specifically transport NMDAR subunit 2 A and 2B in neurons, respectively, are involved in the pathogenesis of psychiatric disorders." (PMID 39885501, 2025).
KIF17 also shares sentences with these, for which no sentence is quoted: Blindness (1 paper); Cirrhosis (1); glioma (1); microphthalmia (1); retinal degeneration (1).